HARS2 (histidyl-tRNA synthetase 2, mitochondrial)
Description:
Mitochondrial aminoacyl-tRNA synthetase that catalyzes the ATP-dependent ligation of histidine to the 3'-end of its cognate tRNA, via the formation of an aminoacyl-adenylate intermediate (His-AMP).
Synonyms: HisRS; HARSL; HARSR; HO3; PRLTS2
Tractability: PROTAC: ubiquitination databases record sites on it; its protein half-life has been measured.
Gene: Protein-coding gene on chromosome 5 (140,691,430 to 140,699,308, forward strand). Ensembl gene ENSG00000112855.
Subcellular location: Mitochondrion
Subcellular location (Human Protein Atlas): Mitochondria
Pathways (Reactome):
Metabolism of proteins: Mitochondrial tRNA aminoacylation
Gene Ontology:
Molecular function: histidine-tRNA ligase activity; protein binding; RNA binding; ATP binding
Biological process: histidyl-tRNA aminoacylation; mitochondrial translation; translation; tRNA aminoacylation for protein translation
Cellular component: mitochondrion; mitochondrial matrix; cytoplasm
Genetic constraint (gnomAD): Loss-of-function variants: 34 observed, 52.32 expected, observed/expected ratio (o/e) 0.65, 90% interval 0.49 to 0.87. The upper end of that interval is the gene's LOEUF score, 0.87, which puts it in group 3 of 6, group 1 being the genes least tolerant of losing a copy. Missense variants: 546 observed, 609.22 expected, observed/expected ratio (o/e) 0.9, 90% interval 0.83 to 0.96. Synonymous variants: 220 observed, 221.69 expected, observed/expected ratio (o/e) 0.99, 90% interval 0.89 to 1.11.
Gene-disease validity (ClinGen):
ClinGen rates the evidence that HARS2 causes each of these diseases.
Perrault syndrome 2 (autosomal recessive): Limited. Any Perrault syndrome in which the cause of the disease is a mutation in the HARS2 gene.
Homologues: Orthologues: chimpanzee HARS2 (97% identical), macaque HARS2 (95% identical), rabbit HARS2 (89% identical), pig HARS2 (89% identical), dog HARS2 (88% identical), guinea pig HARS2 (87% identical), mouse Hars2 (84% identical), rat Zmat2 (84% identical), zebrafish hars (64% identical), tropical clawed frog hars1 (58% identical), Drosophila melanogaster HisRS (54% identical), Caenorhabditis elegans hars-1 (48% identical). Paralogues in human: HARS1 (72% identical).
Diseases named in the same sentence as HARS2 in open-access papers:
HARS2 is named in the same sentence as 26 diseases in open-access papers, as found by Europe PMC text mining. Sharing a sentence is not in itself a finding about the gene and the disease. The quoted sentences say what the papers report.
Perrault syndrome (22 papers, 2012 to 2025). Perrault syndrome (PS) is characterized by the association of ovarian dysgenesis in females with sensorineural hearing impairment. "Biallelic pathogenic variants in either HARS2 (mtARS for histidine) or LARS2 (mtARS for leucine) result in Perrault syndrome, which associates HI with ovarian dysfunction in females, and manifests as NSHI in males." (PMID 39062730, 2024). "Mirroring a joint pathogenetic pathway for different variants of Perrault syndrome, Clpp-KO testes from the early stages of spermatogenesis contain elevated amounts of HARS2." (PMID 38927630, 2024). "The selective impact of CLPXP on mtLSU was surprising, because Perrault syndrome is triggered by mutant HARS2/LARS2/ERAL1, all of which are associated with the mtSSU." (PMID 38139332, 2023). "Patient 17 carries two compound heterozygous variants in the HARS2 gene, which is associated with Perrault syndrome 2 (MIM: # 614926)." (PMID 36979683, 2023). "In the heatmap among DNA/RNA processing factors, the early and consistent accumulation of mitochondrial factors was evident, including PEO1, ERAL1, and HARS2, whose mutations are known to trigger Perrault syndrome with ovarian germ cell failure." (PMID 36611846, 2022). "Biallelic variants in HARS2 are associated with Perrault syndrome, a rare recessive condition characterized by sensorineural hearing loss in both sexes and primary ovarian insufficiency in 46,XX females." (PMID 31827252, 2020). "HARS2 has been associated with Perrault syndrome, which is an autosomal recessive disorder characterized by ovarian dysgenesis and deafness." (PMID 33095795, 2020). "Our findings further expanded the existing spectrum of HARS2 variants and Perrault syndrome phenotypes, which will assist in molecular diagnosis and genetic counselling of patients with HARS2 mutations." (PMID 33228777, 2020). "As panel and exome testing becomes more commonplace for etiological diagnosis in hearing loss, we expect more cases of HARS2-associated Perrault syndrome will be recognized." (PMID 31827252, 2020). "Two unrelated women with Perrault syndrome from consanguineous Moroccan families were homozygous for the same variant, HARS2 c.1010A>G p.(Tyr337Cys)." (PMID 31827252, 2020). "The report of these families increases the number of described families with HARS2 variants and either Perrault syndrome or SNHL to nine." (PMID 31827252, 2020). "In 2011, Mutations in HARS2 were first identified as a cause of Perrault syndrome by genome-wide linkage analysis and candidate gene sequencing." (PMID 33228777, 2020). "The typical clinical phenotype of Perrault syndrome was observed in four families previously reported with biallelic HARS2 variants." (PMID 33228777, 2020). "These novel variants further expanded the existing spectrum of HARS2 variants and phenotypes of Perrault syndrome or SNHL, which can assist in molecular diagnosis and genetic counselling of patients with SNHL." (PMID 33228777, 2020). "Previously, six unrelated families have been reported with variants in HARS2 which cause Perrault syndrome." (PMID 31827252, 2020). "The present cohort was too small to elucidate a relation between genotypes and phenotypes, as 16 variants of HARS2 have been associated with deafness or Perrault syndrome in 10 cases to date." (PMID 33228777, 2020). "This lack of biallelic loss-of-function variants likely indicates that HARS2, along with the other Perrault syndrome associated genes, is essential and that complete loss-of-function would result in lethality." (PMID 31827252, 2020). "Mutations in HARS2 are one of the genetic causes of Perrault syndrome, characterized by sensorineural hearing loss (SNHL) and ovarian dysfunction." (PMID 33228777, 2020).
Perrault syndrome (continued). "In the HARS2 gene, a compound heterozygous mutation encoding both L200V and V368L is linked to Perrault Syndrome, and these substitutions alter highly conserved residues in the catalytic domain." (PMID 24917879, 2014). "Mutations in HARS2, encoding the mitochondrial histidyl-tRNA synthetase (mt-HisRS), have been associated with Perrault syndrome in a family with five members affected (OMIM#614926)." (PMID 24639874, 2014). "Patient 17, presenting two compound heterozygous novel variants in the HARS2 gene causative of Perrault syndrome, also belongs to the second group and clinical features such as primary amenorrhea and infertility would only be evaluated when she reaches the pubertal stage." (PMID 36979683, 2023). "Moreover, functional null mutations of Hars2 (encoding mitochondrial histidyl tRNA synthetase) cause Perrault syndrome, which is characterized by ovarian dysgenesis and sensorineural hearing loss." (PMID 34220452, 2021). "Biallelic variants in HARS2 have been associated with Perrault syndrome, a rare autosomal recessive disease characterised by variable degrees of sensorineural hearing loss (SNHL) in both sexes and primary ovarian insufficiency (POI) in 46, XX karyotype females." (PMID 31827252, 2020). "Combined with preexisting clinical reports, Perrault syndrome may be latent in some families with non-syndromic deafness associated with HARS2 mutations." (PMID 33228777, 2020). "Perrault syndrome may be latent in some families with non-syndromic deafness associated with HARS2 mutations." (PMID 33228777, 2020). "Interestingly, hearing problems are present also in patients with PCH6 (due to RARS2 mutations) or Perrault syndrome (caused by LARS2 or HARS2 mutations)." (PMID 24639874, 2014). "Mutations in HARS2 cause Perrault syndrome with ovarian dysgenesis and hearing loss." (PMID 23251452, 2012). "Biallelic pathogenic variants in HARS2 and LARS2 result in Perrault syndrome, which associates hearing impairment with ovarian dysfunction and, occasionally, a variety of neurological signs." (PMID 39062730, 2024). "Interestingly, subjects with biallelic HARS2 pathogenic variants, like the five reported in this study, do not show neurological signs or they may be very subtle, in contrast to what is observed for other genes involved in Perrault syndrome." (PMID 39062730, 2024). "Variants in HARS2 and LARS2 are associated with Perrault syndrome manifesting with a wide range of neurological symptoms, variable progression of hearing loss and POI." (PMID 37148394, 2023). "Mutations in histidyl-tRNA synthetase 2, mitochondrial (HARS2), and leucyl-tRNA synthetase 2, mitochondrial (LARS2), are frequently associated with Perrault syndrome, which often leads to neuropathic hearing impairment and ovarian dysfunction in women." (PMID 35805194, 2022). "As variants in other tRNA processing factors such as PRORP, HARS2, and LARS2 are a known cause of PRLTS, a common mechanism of disease pathogenesis begins to emerge for Perrault syndrome." (PMID 34943861, 2021). "To date, biallelic variants in six causative genes have been associated with Perrault syndrome:HSD17B4 (MIM 233400), HARS2 (MIM 614926), LARS2 (MIM 615300), CLPP (MIM 614129), C10orf2 (MIM 616138), and ERAL1 (MIM 607435)." (PMID 31827252, 2020). "The diagnosis of Perrault syndrome is confirmed by the presence of biallelic pathogenic variants in one of six genes, such as CLPP, ERAL1, HARS2, HSD17B4, LARS2, and TWNK." (PMID 33228777, 2020). "Mutations of five (mt) aaRS genes cause syndromic forms of deafness, including Perrault syndrome (LARS2, HARS2), Charcot Marie Tooth disease type 2N (AARS) and pontocerebellar hypoplasia type 6 (RARS2)." (PMID 25807530, 2015). "Genetic studies indicate that mutations in mitochondrial HARS2 and LARS2 are both linked to Perrault Syndrome." (PMID 24917879, 2014).
Perrault syndrome (continued). "Mutations in the mitochondrial tRNA–aminotransferases for histidine and leucine, HARS2 and LARS2, cause the typical features of Perrault syndrome, while mutations in the mitochondrially encoded tRNA sequences trigger different and mostly neurodegenerative phenotypes, including progressive deafness." (PMID 38927630, 2024). "Pathogenic/likely pathogenic variants in HARS2, CLPP, LARS2, TWNK, ERAL1, and PROPR may cause Perrault syndrome-related OD." (PMID 38812815, 2024). "Neurological presentations are commonly associated with Perrault syndrome and although no phenotype genotype links have yet been established for HARS2, all individuals with disease associated HARS2 variants should have a full clinical neurological assessment." (PMID 31827252, 2020). "In LARS2- and HARS2-associated Perrault syndrome, no data were published about the brain imaging, while in CLPP-associated Perrault syndrome, high signal intensity in the corticospinal tract deep white matter could be found." (PMID 31852434, 2019). "Recently, mutations in mt-aaRS (ARS2) and cytoplasmic aaRS (ARS) have been associated with human diseases such as Charcot-Marie-Tooth disease, Perrault syndrome (LARS2, HARS2), and pontocerebellar hypoplasia, all of which include sensorineural hearing impairment." (PMID 25807530, 2015). "This consistency contrasts with other genes associated with Perrault syndrome where brain white matter changes are variable in frequency, from commonly present in individuals with CLPP-associated Perrault syndrome to absent with HARS2-associated disease." (PMID 40043708, 2025).
hearing loss (7 papers, 2014 to 2024). "In the subjects with HARS2 pathogenic variants who have been reported in the literature, the onset of hearing impairment occurs early in the infancy (prelingual), like in our five patients." (PMID 39062730, 2024). "Here, we report a recurrent variant in HARS2 in association with sensorineural hearing loss." (PMID 31827252, 2020). "Dysfunction of some mitochondrial aminoacyl-tRNA synthetases (encoded by the KARS1, HARS2, LARS2 and NARS2 genes) results in a great variety of phenotypes ranging from non-syndromic hearing impairment (NSHI) to very complex syndromes, with a predominance of neurological signs." (PMID 39062730, 2024).
deafness (5 papers, 2014 to 2022). An inherited or acquired condition characterized by the complete loss of the ability to hear from one or both ears. "In this study, we generated a Hars2 conditional knockout mice to investigate the function of HARS2 in hearing and its pathogenic mechanism for deafness." (PMID 34975414, 2021).
COVID-19 (1 paper, 2021). A disease caused by infection with severe acute respiratory syndrome coronavirus 2. "In the contrary, HARS2 was significantly increased in COVID-19 patient-derived samples and the SARS-CoV-2-infected cell lines at protein levels." (PMID 35153822, 2021). "More importantly, this work identifies TARS2, HARS2, and EARS2 as potential key factors involved in COVID-19." (PMID 35153822, 2021). "Although there has been no study to report the tRNA-like elements regulated by TARS2, HARS2 or EARS2, the investigation of the aaRSs-mediated control of viruses or host mRNAs, as well as the function of tRNA-like structures will reveal novel molecular mechanisms for COVID-19." (PMID 35153822, 2021).
cancer (2 papers, 2007 to 2020). A tumor composed of atypical neoplastic, often pleomorphic cells that invade other tissues. "There are a few aaRSs that are downregulated in multiple cancer types, including HARS2 (n = 6), WARS1 (n = 4), CARS2 (n = 4), IARS1 (n = 3), RARS2 (n = 3), VARS2 (n = 3), and AIMP3/EEF1E1 (n = 3), suggesting these aaRSs may possess certain specific cancer-inhibiting roles." (PMID 33266490, 2020).
tumour (2 papers, 2007 to 2025). "Eight genes (CDH23, HARS2, LLGL2, LTBP1, MAP6D1, MIPOL1, SCYL3, ZNF418) showed some degree of promoter methylation in at least one tumour, but only MIPOL1 exhibited probable homozygous methylation in more than one sample." (PMID 39794353, 2025).
HARS2 also shares sentences with these, for which no sentence is quoted: ovarian dysfunction (4 papers); ovarian dysgenesis (3); infection (2); Perrault syndrome 2 (2); sensorineural hearing loss (2); (HUPRA) syndrome (1); Charcot-Marie-Tooth disease (1); epilepsy (1); Hearing impairment (1); Infertility (1); Leigh syndrome (1); leukodystrophies (1); mitochondrial disease (1); pneumonia (1); pontocerebellar hypoplasia (1); Primary amenorrhea (1); pulmonary hypertension (1); Sensorineural hearing impairment (1); type 2 diabetes (1); viral infections (1).